METTL3 (methyltransferase 3, N6-adenosine-methyltransferase complex catalytic subunit)
Diseases named in the same sentence as METTL3 in open-access papers (continued):
Sharing a sentence is not in itself a finding about the gene and the disease.
tumor (continued). "Interestingly, in GCT, a low expression level of METTL3 serves as an unfavourable prognostic marker, promoting the proliferation, migration and invasion of GCT cells by regulating tumour EMT processes and immune responses." (PMID 38332508, 2024). "PARP1 inhibitors can also depress METTL3 expression, resulting in a decreased M6A level of LPAR5 mRNA A1881, consequently leading to decreased stability of LPAR5 mRNA and exhibiting a synergistic effect of tumor growth suppression with radiotherapy." (PMID 38473842, 2024). "In summary, METTL3 and YTHDF2 may act as “oncogenes” in HCC, facilitating tumor angiogenesis and malignant progression." (PMID 39295872, 2024). "Moreover, the IHC staining also confirmed that METTL3, p-JAK2/p-STAT3, GLUT1, and Ki67 were significantly elevated in the mice tumor with injection of MHCC97H mixed with Exo-incubated macrophages or M2 macrophages." (PMID 39247822, 2024). "Interestingly, as an inhibitor of METTL3, STM2457 also had a therapeutic effect in mice with AML, improving the survival of mice by reducing the number of leukemic stem cells and tumor cells." (PMID 39033180, 2024). "In addition, various m6A methylation modulators such as METTL3, FTO, and IGF2BP have been found to have some relationship with tumor prognosis." (PMID 39033180, 2024). "Knockdown of METTL3 has been observed to alter the malignant phenotype across various tumor types, whereas multiple studies have indicated that elevated expression of METTL14 inhibits tumor proliferation and migration via m6A-dependent mechanisms." (PMID 38965238, 2024). "The direct induction of CD33+CD11b+HLA-DR-myeloid-derived suppressor cells (MDSCs) and tumor-derived MDSC induction in vitro were observed to be attenuated in the absence of METTL3." (PMID 39199429, 2024). "Additionally, H3K18 lactylation induced by lactate accumulation upregulates METTL3 expression and subsequently mediates m6A modification of JAK1, thereby enhancing the immunosuppressive roles of CRC tumor‐infiltrating myeloid cells." (PMID 38721006, 2024). "To evaluate the effect of targeting METTL3 on the in vivo efficacy of PTX and CBP, we established the xenograft tumor model by subcutaneously injecting 5 × 106 NCI-H460 cells and randomly divided mice into two batches (4 groups/batch) when the tumor volume reached 80-90 mm3." (PMID 39309428, 2024). "Similarly, METTL3, WTAP, and YTHDC1 are involved in MAPK pathway activation, enhancing tumor neovascularization in CRC." (PMID 39098905, 2024). "In addition, METTL3 activates PI3K/Akt and β-catenin pathways to promote tumor cell progression and survival rate." (PMID 38075202, 2024). "It has been reported that METTL3 and METTL14 promote the tumor initiation and progression in PC." (PMID 38216561, 2024). "Recent studies have discovered that stem cell markers, such as doublecortin-like kinase (DCLK1) and RNA modification by methyltransferase-like 3 (METTL3), play a role in recruitment of CXCR2+ MDSCs to modulate tumor immunity through the CXCL1-CXCR2 axis in CRC mouse models." (PMID 38750114, 2024). "Similarly, ALKBH1 overexpression promotes metastasis in CRC through modifying METTL3 mRNA m1A levels, resulting in reduced protein translation, increased m6A demethylation of SMAD7 mRNA, and enhanced tumor migration and invasion." (PMID 38317214, 2024). "In order to further explore the effect of METTL3 on endostar combined with cisplatin in the treatment of NSCLC mice, we constructed METTL3 overexpression and knockdown cell lines to construct a mouse tumor-bearing model." (PMID 38331776, 2024). "Targeting m6A modification by STM2457, a small-molecule inhibitor of METTL3, could downregulate MYCN expression and attenuate tumor proliferation." (PMID 38745192, 2024). "METTL3 depends on YTHDF2 to promote the m6A modification of NUCB1, thereby regulating ATF6, blocking gemcitabine (GEM)-induced autophagy and enhancing the anti-tumor effect of GEM." (PMID 39468015, 2024).
tumor (continued). "METTL3 in NK cells is essential for maintaining homeostasis, as it promotes the infiltration and functionality of NK cells in the TME, thereby enhancing anti-tumor immunity and increasing overall survival in mice." (PMID 39759516, 2024). "Thus, we first examined the expression levels of METTL3, METTL14, WTAP, RBM15, FTO, and ALKBH5 transcripts in tumor samples and corresponding normal samples using the GEPIA database." (PMID 38665783, 2024). "Additionally, we identified a potential link between METTL3 and DLAT in cuproptosis‐related tumour development, providing a new strategy for cancer prevention and treatment." (PMID 38429907, 2024). "Phosphatase and tensin homolog (PTEN) is a tumor suppressor gene, and its mRNA stability is regulated by LINC00470/METTL3-mediated m6A modification, resulting in decreased stability of PTEN mRNA and activation of the protein kinase B (AKT) pathway, thereby inhibiting the cellular autophagy process." (PMID 39468015, 2024). "METTL3 depletion increased APC expression and reduced tumor size of athymic nude mice." (PMID 38721006, 2024). "Through in vivo and in vitro experiments, we found that METTL3 could enhance the expression of SNAIL protein through m6A modification, thereby promoting EMT in tumor cells." (PMID 38605400, 2024). "The METTL3–METTL14 dimer mediates the deposition of m6A on mammalian RNA, functioning as both oncogenes and tumor suppressors in different tumors or even within the same tumor." (PMID 39445003, 2024). "Furthermore, evidence has confirmed that IGF2BP2/3 mediates the pro-angiogenic effects of METTL3 in CRC and, together, promotes tumor progression." (PMID 39033180, 2024). "The suppression of tumour proliferation observed in METTL3 KO may be mediated by YTHDC1, while the effect of METTL3 inhibition is mainly mediated by the YTHDF family." (PMID 39568154, 2024). "Moreover, silencing METTL3 reduces PIN1 overexpression-induced colony formation in MCF7 cells and enhances tumor growth in 4T1 cells in mouse models." (PMID 38961497, 2024). "Mechanistically, METTL3 inhibition triggers an interferon response within tumour cells, amplifying the anti‐tumour immune response, along with deletion of the m6A reader protein YTHDF2 in tumours inhibiting major histocompatibility complex (MHC)‐I degradation." (PMID 39568154, 2024). "Absence of METTL3 protein imbalances NK cells, thereby inhibiting NK cells from playing a role in immunity, leading to rapid tumor cell growth." (PMID 39072324, 2024). "Although the KO of METTL3 or the application of METTL3 inhibitors in tumour cells has been shown to augment the efficacy of ICB therapy, there is a lack of attention to the impact of METTL3 on T cells within the tumour microenvironment." (PMID 39568154, 2024). "study, which found that METTL3/METTL14 upregulation could enhance OSCC chemoresistance and accelerate tumor growth in vivo." (PMID 38966069, 2024). "Therefore, we first examined the subcellular localization of METTL3 and METTL14 through co-immunofluorescence staining in tumor tissues and EC109 cells." (PMID 38965238, 2024). "miR-33a, which acts as a tumor suppressor in several cancers, inhibits the proliferation and migration of cancer cells by targeting the 3′-UTR of METTL3, thus reducing the expression of METTL3." (PMID 39087001, 2024). "Moreover, FTO and ALKBH5 negatively regulated METTL3 and positively regulated METTL14 expression levels, enhancing their role as tumor suppressors of CRC." (PMID 37580808, 2023). "Furthermore, we found that METTL3 was significantly positively correlated, albeit moderately, with NCBP1 using linear regression analysis in DLBCL tumor tissues from the GEPIA data set (r = 0.7; P < 0.0001)." (PMID 37244946, 2023). "Further investigation verified that YTHDF2 could recognize the abundance of m6A-modified mRNA of LHPP and NKX3-1 induced by METTL3 and degrade them, thereby promoting AKT phosphorylation and tumour progression." (PMID 37284313, 2023).
tumor (continued). "Similarly, in another common type of lung adenocarcinoma (LUAD), METTL3 increases the stability of lncRNA LCAT3, leading to the binding of FUBP1, activating the oncogenic molecule c-MYC, and promoting tumor proliferation, invasion, and metastasis." (PMID 37063421, 2023). "Moreover, the accretion of lactate within the tumor microenvironment has been shown to instigate histone H3K18 lactylation, engendering elevated expression of Mettl3 and m6A modification of Jak1 mRNA within tumor‐infiltrating myeloid cells." (PMID 38034101, 2023). "To this end, we inquired our in-house RNA sequencing (RNA-seq) database of 17 paired NAFLD-HCC and adjacent non-tumor tissues, revealing 2,028 genes that were overexpressed in NAFLD-HCC (fold change >1.5; p < 0.005), and METTL3 was one of the top RNA modification genes among the gene candidates." (PMID 37586322, 2023). "We compared METTL3 expression levels in CRC tumor tissues and adjacent nontumor tissues by immunohistochemistry (IHC)." (PMID 36348020, 2023). "Consistent with our hypothesis, liver-specific METTL3 knockin increased NAFLD-HCC incidence and tumor burden." (PMID 37586322, 2023). "Meanwhile, in tumor-infiltrating myeloid cells (TIMs), METTL3 mediates the m6A modification of JAK1 RNA and enhances the translation efficiency of the JAK1 protein, followed by the activation of STAT3 phosphorylation to promote tumor cell growth." (PMID 37996892, 2023). "It was observed that in Mettl3-cKO mice, Gr-1+ MDSCs were marginally present in PerC until four to five weeks after ID8 cell inoculation but were dramatically increased in the late phase (eight to nine weeks) of tumor progression." (PMID 37932814, 2023). "It is now believed that METTL3 regulates the metabolic reprogramming of tumors by modulating the expression of glucose transporters (GLUTs), lactate dehydrogenase (LDHA) and enolase 1 (ENO1) in tumor cells." (PMID 37996892, 2023). "These outcomes suggest that the tumor suppressor effect of ANXA10 is related to m6A; ANXA10 may regulate HNRNPA2B1, IGF2BP3, METTL3, RBM15, YTHDF1 and YTHDF2 to affect the methylation level of LIHC." (PMID 36709331, 2023). "Mechanistically, the Mettl3-mediated increase in the receptor tyrosine kinase AXL translation promotes epithelial-mesenchymal transition (EMT), leading to cellular proliferation, migration, invasion, and tumor formation." (PMID 37007040, 2023). "Further research found that METTL3 promotes the translation efficiency of JAK1 mRNA in the manner of m6A-YTHDF1 and subsequently strengthens STAT3 signaling in TIMs, then drives the immunosuppressive activity of TIMs at tumor sites." (PMID 37152066, 2023). "MiR-4443 targets METTL3 in NSCLC, thereby upregulating ferroptosis suppressor protein 1 (FSP1) expression in an m6A-dependent manner, inhibiting cisplatin-induced iron death, and promoting tumor proliferation." (PMID 37151887, 2023). "These analyses support the notion that overexpression of METTL3 in LIHC and other tumor types could be attributed to hypomethylation of its promoter region." (PMID 38012755, 2023). "The direct intermolecular regulatory mechanism by which METTL3 affects tumour progression and survival was not clarified in detail, and we will be further studied in the future." (PMID 36765397, 2023). "The m6A writers METTL3 and WTAP were found to be upregulated in GBM and promote tumour growth and progression, and it may be that their upregulation contributes to increased m6A-containing R loops, and subsequent genomic instability, in GBM." (PMID 37444417, 2023). "Moreover, Western blotting analysis indicated that METTL3 and STAT3 were highly expressed in HCC tissues in comparison with paired non-tumor tissues (n = 10)." (PMID 37231451, 2023). "Since the m6A writer METTL3 is upregulated in RMS, we speculated that it could play a role in tumor growth." (PMID 37019933, 2023). "Among these, METTL3 promotes aerobic glycolysis and ESCC tumour development." (PMID 36855123, 2023).
tumor (continued). "In addition, m6A methyltransferase METTL3 increased GNAS and GADD45 in an m6A-dependent manner, which promoted tumor growth and hormone secretion." (PMID 36831377, 2023). "Further, we used METTL3-WT, METTL3-Δ238, or METTL3-Δ198 to, respectively, complement MDA-MB-231 METTL3 KO cells, and injected these cells orthotopically into the mammary fat pads of mice and performed bi-weekly measurement of tumor volume by caliper." (PMID 37589705, 2023). "In addition, RT-qPCR and immunohistochemical staining also showed that celastrol administration downregulated Claspin, Bcl-2, METTL3, and YTHDF3 in the xenograft tumor tissues." (PMID 38110764, 2023). "have shown that METTL3 depletion in macrophages activates the NF-κB pathway and STAT3 signaling, resulting in increased infiltration of M1 and M2 TAMs and Treg cells into the tumor, ultimately remodeling the tumor microenvironment." (PMID 38187373, 2023). "We isolated T cells from tumor-bearing mice and cultured T cells in a conditioned medium from murine Hepa1-6 cells with or without METTL3 knockout." (PMID 37586322, 2023). "The METTL3/IGF2BP3/HDGF axis promotes tumor angiogenesis, tumor growth, and liver metastasis." (PMID 37298373, 2023). "Increased METTL3 and LEF1 levels activate the Wnt pathway and promote tumour progression." (PMID 37284313, 2023). "METTL3 increased HK2 and SLC2A1(GLUT1) mRNA stability and transcription levels through an m6A-IGF2BP2/3-dependent mechanism, then activated CRC glucose metabolism to facilitate cell proliferation and tumor growth in vitro and in vivo." (PMID 37152066, 2023). "Previous studies have found that expression of METTL3 and WTAP are regulated by androgen in PC cell lines, as well as increased expression of METTL3 plays a pro-tumor role in PC, while METTL3 silencing resulted in upregulation of AR, together with 134 AR-regulated genes." (PMID 38042806, 2023). "Thus, studies on the regulatory effect of METTL3 on MYC expression, mediated either directly or indirectly by m6A, in the context of tumor growth are expected to provide a new therapeutic strategy for tumors." (PMID 37996892, 2023). "The most typical family member METTL3/METTL14 forms a methyltransferase complex involved in N6-methyladenosine (m6A) modification of RNA, regulating tumor proliferation, metastasis and invasion, immunotherapy resistance, and metabolic reprogramming of tumor cells." (PMID 37533128, 2023). "Interestingly, in medulloblastoma, METTL3 acts directly on PTCH1 and GLI2, important factors in the Hedgehog pathway, to promote tumor progression." (PMID 37996892, 2023). "The deletion of METTL3 in macrophages impairs the YTHDF1-mediated translation of SPRED2, which enhances the activation of NF-kB and STAT3 through the ERK pathway, leading to increased tumor growth and metastasis." (PMID 37928272, 2023). "Since METTL3c was largely absent within endogenous METTL3, combined with data from m6A dot blots and tumor cell growth assays showing that METTL3-2MA functioned similarly to METTL3-WT, we did not investigate METTL3c in the following study." (PMID 37589705, 2023). "METTL3 phosphorylation in ERK-activated tumor cells contributes to CRC tumorigenesis, suggesting that a new function of ERK in regulating m6A methylation exists and that the activation of the ERK-METTL3/WTAP axis promotes tumorigenesis." (PMID 37391814, 2023). "In addition, METTL3, YTHDF3 and IGF2BP3 affect tumor angiogenesis by regulating the expression of VEGF." (PMID 38053093, 2023). "FTO, RBMX, METTL3, and METTL14, have been demonstrated to be tumor proto-oncogenes or biomarkers through m6A, with METTL3 serving as a pathological diagnostic index and potential therapeutic target for ESCA, and with RBMX encoding HNRNPG to affect m6A, also a member of the hnRNPs family." (PMID 36195940, 2022). "METTL3 expression was significantly higher in primary tumour compared to non-malignant prostate tissue (p < 0.0001), and significantly higher in cases with BCR (p < 0.05)." (PMID 36291932, 2022).
tumor (continued). "There was a negative correlation between the abundance of F. nucleatum and METTL3 levels in CRC tumor tissues, as well as a negative correlation between the expression levels of METTL3 and KIF26B in CRC tumor tissues." (PMID 35273176, 2022). "While METTL3 expression is significantly higher in tumour compared with non-malignant prostate tissue, METTL3 is deleted in a subset of patients." (PMID 36733939, 2022). "STM2457 combined with anti-PD-1 therapy also can achieve good anti-CRC tumor effect, but no METTL3 inhibitor has been found to be used for CRC anti-angiogenesis." (PMID 36114893, 2022). "In addition, Peptide 17 is able to repress N6-methyladenosine (m6A)’s methyltransferase 3 (METTL3) expression, leading to a decrease in YAP1 mRNA expression and of the consequent tumour-promoting effects in GC." (PMID 35565411, 2022). "Moreover, METTL3 deletion aggravated the IKE‐induced increase in MDA concentration and decrease in GSH/GSSG ratio in subcutaneous xenograft tumours." (PMID 35522946, 2022). "Analysis of protein expression in non-malignant and tumour specimens identified that METTL3 nuclear expression was higher in tumour specimens compared with non-malignant prostate tissue (p = .011)." (PMID 36733939, 2022). "Notably, ASP/NAM-mediated m6A reduction occurred in additional tumor cell lines following ASP/NAM treatment, which correlated with enhanced METTL3 acetylation." (PMID 36289222, 2022). "Conversely, suppressing m6A levels via METTL3‐siRNA treatments suppressed SLC7A11 expression, allowing increased accrual of lipid ROS and consequent induced ferroptosis, thus preventing tumorigenesis of HB cancer cells and tumour growth in mice." (PMID 35604883, 2022). "Consistent with mRNA expression, METTL3 protein expression was also significantly higher in tumour as compared with non-malignant specimens (p < 0.0001)." (PMID 36291932, 2022). "Depletion of METTL3 blocks invasion, migration, and EMT of cancer cells and tumor metastasis." (PMID 36071523, 2022). "Knockdown of METTL3 in Luminal A and triple negative cell lines can reduce methylation levels, reduce tumor cell proliferation, accelerate apoptosis and inhibit tumor growth in a BALB/c xenograft model." (PMID 36008936, 2022). "METTL3 participates in cell proliferation, invasion, migration, metastasis, angiogenesis, glycolysis, drug resistance, and tumor microenvironment, dependent or not on catalytic activity." (PMID 35331234, 2022). "One study demonstrated a negative correlation between METTL3 or METTL14 and STAT1 in patients with low mutational tumor burden and tumors associated with the mismatch-repair-proficient or microsatellite instability-low (pMMR-MSI-L) genotypes." (PMID 35885000, 2022). "The heterogeneity of METTL3 mRNA expression in PCa patients suggests METTL3 has complex roles in PCa and does not function uniquely as an oncogene or tumour suppressor." (PMID 36291932, 2022). "Furthermore, knockdown of METTL3 potently reduces CD33+ CD11b+ HLA-DR− MDSCs and tumor-derived MDSCs in CD33+ or HeLa cells." (PMID 36071523, 2022). "METTL3 and HNRNPA2B1 expression was reduced in tumor xenografts with LINC01833 suppression." (PMID 35441574, 2022). "Interestingly, HBXIP also facilitates METTL3 expression by restraining tumor suppressor miRNA let-7g, which stimulates METTL3 expression through targeting its 3′UTR, thereby forming a positive feedback loop of HBXIP/let-7g/METTL3/HBXIP." (PMID 35462896, 2022). "METTL3 nuclear expression was also found to be higher in those patients with extraprostatic tumour extension (p = .032), than those without." (PMID 36733939, 2022). "As both the m6A writer METTL3 and the reader YTHDF2 positively regulate the anti-tumor immunity of NK cells, METTL3- and YTHDF2-mediated m6A methylation might be important regulators of anti-tumor immunity and homeostasis of NK cells." (PMID 35296338, 2022).